UGT2B15 (UDP glucuronosyltransferase family 2 member B15)
Diseases named in the same sentence as UGT2B15 in open-access papers (continued):
Sharing a sentence is not in itself a finding about the gene and the disease.
melanoma (2 papers, 2012 to 2022). A malignant, usually aggressive tumor composed of atypical, neoplastic melanocytes. "Treatment of WM3211 or metastatic melanoma cell lines with anti-cancer agents (including vemurafenib) induced expression of UGT2B7, UGT2B10 and UGT2B15 demonstrating that melanoma cells retain the ability to re-express these same three UGTs." (PMID 23110092, 2012). "Only a few reports have been published, including research on UGT expression in melanocytes derived from newborn foreskin tissues, with UGT2B isoforms (UGT2B7, UGT2B10, and UGT2B15) being expressed primarily in normal melanocytes as well as in a primary melanoma cell line." (PMID 35682955, 2022). "Interestingly we demonstrate that UGT2B7, UGT2B10 and UGT2B15 can be re-expressed in melanoma cells in response to the anti-cancer agents." (PMID 23110092, 2012). "Consistent with the UGT expression pattern observed in melanocytes, the primary melanoma cell line WM115 exhibited only UGT2B7, UGT2B10 and UGT2B15 expression." (PMID 23110092, 2012).
prostate tumors (2 papers, 2020). "Similar to normal prostate tissue, prostate tumours expressed several UGT2B mRNAs, including UGT2B17 but also UGT2B4, UGT2B7, UGT2B10, UGT2B11, UGT2B15 and UGT2B28." (PMID 32047296, 2020). "Interestingly, among the common up-regulated targets, UGT2B15 and HOTAIR were described to be inhibited by AR in prostate tumors and activated by ESR1." (PMID 32041153, 2020).
depression (1 paper, 2024). "The CAI values of the genes associated with depression displayed values ranging from 0.713 (UGT2B15) to 0.85 (CYP1A2)." (PMID 38346990, 2024).
endometrial cancer (1 paper, 2022). Primary or metastatic malignant neoplasm involving the endometrium (mucous membrane that lines the endometrial cavity). "To evaluate our hypothesis that UGT2B15 is a target for inhibitory regulation by IGF1, we chose to measure UGT2B15 mRNA levels in endometrial cancer cells." (PMID 35626664, 2022).
esophageal cancer (1 paper, 2023). A primary or metastatic malignant neoplasm involving the esophagus. "In this study, by analyzing our previous AR cistromes and androgen-regulated transcriptomes, we find that AR upregulates the expression of UGT2B15 in esophageal cancer cells." (PMID 38136265, 2023). "Our findings reveal the molecular mechanisms of AR in esophageal cancer invasion and identify the AP1-directed AR transcriptional activation of UGT2B15 as a potential therapeutic target for esophageal cancer metastasis." (PMID 38136265, 2023). "In this study, we revealed that AP-1 guides AR binding and collaborates with AR to upregulate target gene UGT2B15 expression to enhance esophageal cancer cell invasion and metastasis." (PMID 38136265, 2023). "Pharmacological inhibition of AR and AP-1 can effectively block the expression of UGT2B15, thus inhibiting the invasion and metastasis of male esophageal cancer." (PMID 38136265, 2023). "Although UGT2B15 may influence the expression of COL5A1 and MFAP5, the functional role of these two genes in UGT2B15-induced esophageal cancer cell invasion and metastasis needs to be further clarified by rescue experimental validation." (PMID 38136265, 2023). "Importantly, genetic or pharmacological inhibition of AP-1 relieves AR-mediated UGT2B15 activation, leading to esophageal cancer cell invasion inhibition." (PMID 38136265, 2023).
hepatoma (1 paper, 2015). "Among these DME genes, the downregulation of CYP1B1, CYP8B1, GSTM2, GSTP1, UGT2B15, and UGT3A2 in hepatoma cells could be explained by DNA methylation status." (PMID 26421064, 2015).
hypogonadism (1 paper, 2025). A disorder characterized by decreased function of the gonads. "Protein-coding variants in several liver genes, such as PNPLA3, GCKR, SLCO1B1, SERPINA1, HGFAC, and UGT2B15, were significantly associated with total testosterone levels and hypogonadism risk." (PMID 40316537, 2025).
liver disease (1 paper, 2021). "The present study demonstrates a significant decline of CYP1A2 and CYP2C9 abundances in the course of progression of liver disease, and similar trend is observed for UGT2B15)." (PMID 34575411, 2021).
lymph node cancer (1 paper, 2023). A primary or metastatic malignant tumor involving the lymph node. "In a transcriptome dataset of 18 paired ESCC patients, which included 18 adjacent normal esophageal tissues, 18 primary ESCC, and 14 metastatic lymph node cancer samples, we observed that the UGT2B15 was exclusively expressed in tumor tissues and metastatic lymph node samples." (PMID 38136265, 2023).
metastasis (1 paper, 2023). The spread or migration of cancer cells from one part of the body (where they first appeared) to another. "Functional studies have revealed that UGT2B15 promoted invasiveness in vitro and lymph node metastasis in vivo." (PMID 38136265, 2023).
prostate hyperplasia (1 paper, 2025). "Specifically, we demonstrated that the NAF enantiomer upregulated the expression and activity of UGT2B15 in both benign prostate hyperplasia (BPH) rat models and human prostate BPH-1 cells." (PMID 39856707, 2025). "To modulate UGT2B15 expression, we employed siRNA and (R)/(S)-NAF (naftopidil), a chemical inducer of UGT2B15 identified in our previous studies on a prostate hyperplasia model." (PMID 39856707, 2025).
uterine serous papillary carcinoma (1 paper, 2022). "In initial experiments, we measured UGT2B15 mRNA levels in the uterine serous papillary carcinoma cell lines USPC-1 and USPC-2." (PMID 35626664, 2022).
cancer (14 papers, 2012 to 2024). A tumor composed of atypical neoplastic, often pleomorphic cells that invade other tissues. "Epigenetic regulation of UGT2B15 may predispose Asians to altered drug and hormone metabolism and begin to explain the increased risks for adverse drug reactions and some cancers in this population." (PMID 29316660, 2018). "Our study implies that hyper-methylation of UGT2B15 in Asians may affect androgen disposition as compared to the Caucasian population and is a promising avenue for investigating some of the altered risk for androgen-related cancers in these populations." (PMID 29316660, 2018). "We further demonstrated that UGT2B15 drives lymph node metastasis of ESCC by the induction of genes involved in cancer metastasis." (PMID 38136265, 2023). "We further analyzed UGT2B15, UGT2B17, and UGT2B28 to determine whether they were genetically linked to cancer." (PMID 39457450, 2024). "Given the important role of these enzymes in cancer pathology, we hypothesized that UGT2B15 and UGT2B17 are novel targets for inhibitory regulation by IGF1." (PMID 35626664, 2022). "In addition to drugs and chemicals, UGT2B15 and 2B17 have been investigated in relation to risks for cancer and other endocrine diseases." (PMID 29316660, 2018). "Five core ADME genes coding for phase II drug metabolism enzymes showed significant associations of their intratumoral expression levels with OS rates in cancers, including GSTP1, NAT1, UGT1A1, UGT2B15, UGT2B7." (PMID 33202946, 2020). "For example, we identified 41 patients in two cancer types receiving tamoxifen where the genes UGT1A10, UGT2B15, or CYP2D6 were highly expressed." (PMID 29783934, 2018). "Kaplan–Meier plots and logrank tests revealed that six UGT genes were significantly associated with increased overall survival (OS) rates [UGT1A1 (LUSC), UGT1A6 (ACC), UGT1A7 (ACC), UGT2A3 (KIRC), UGT2B15 (BLCA, SKCM)] or decreased OS rates [UGT2B15 (LGG), UGT8 (UVM)] in specific cancers." (PMID 34503303, 2021).
tumor (13 papers, 2012 to 2024). "Our observed association of high UGT2B15 levels with increased OS rates in BLCA might be attributable to its intratumoral glucuronidation of androgens within the tumour as recently suggested." (PMID 34503303, 2021). "PPIB, UGT2B15 and IFI27, which were found in tumour cluster A, were mainly associated with cell survival and apoptosis." (PMID 35109839, 2022). "A total of 281 variants were associated with tumor necrosis and five of these variants, in SLC22A1, SLC22A8, CHST12 and UGT2B15, were also associated with OS, prioritizing these for future research." (PMID 36536332, 2022). "The role of UGT2B15 in inducing tumour progression and drug resistance has been reported in some studies." (PMID 35109839, 2022). "Compared to the parent LNCaP cells, expression of AR, AHR, CDH1, CXCR7, FLNA, ITGA6, and UGT2B15 in tumor was significantly inhibited." (PMID 33808801, 2021). "For UGT2B15, connections between expression and parameters including tumor necrosis, satellite lesions, and pN were significant." (PMID 34337056, 2021). "Immunohistochemical staining of tumor tissue from the xenograft study using anti-UGT2B15 and anti-UGT2B17 antibodies showed that the phenotypic differences between shCtrl and shADRB2-2 cells were maintained also after castration." (PMID 26646591, 2016). "Specifically, in the tumour region, we observed enrichment of PPIB and UGT2B15 and IFI27, NDRG1, BHLHE40 and VEGFA." (PMID 35109839, 2022). "In addition, PGR, as well as UGT2B15 and UGT2B7, which were the non-tumor-related genes identified among the 29 targeted genes, were found to be related to overall survival in CRC patients." (PMID 36843944, 2023). "UGT2B15 and UGT2B7, which are non-CRC tumor-associated genes that were identified in the normal expression group, were found to be correlated with overall survival in CRC patients." (PMID 36843944, 2023). "If UGT2B15 and UGT2B17 are important determinants of the availability of bioactive androgens in the tumor micro milieu in vivo, patients with low ADRB2 expression may have a lower response to androgen-deprivation therapy through lowered UGT2B15 and UGT2B17 protein levels." (PMID 26646591, 2016).
UGT2B15 also shares sentences with these, for which no sentence is quoted: breast tumor (1 paper); cervical cancer (1); colon cancer (1); endocrine diseases (1); esophageal squamous cell carcinoma (1); Laron syndrome (1); liver dysfunction (1); lymph node metastasis (1); metastatic melanoma (1); polycystic ovary syndrome (1); prostate adenocarcinoma (1); renal disorders (1).